MAP3K11 (mitogen-activated protein kinase kinase kinase 11)
Diseases named in the same sentence as MAP3K11 in open-access papers:
MAP3K11 is named in the same sentence as 80 diseases in open-access papers, as found by Europe PMC text mining. Sharing a sentence is not in itself a finding about the gene and the disease. The quoted sentences say what the papers report.
breast carcinoma (17 papers, 2012 to 2024). "Similarly, MAP3K11 was found to be required for chemokine-induced invasiveness of breast cancer cells through its activation of paxillin." (PMID 26717044, 2016).
ovarian carcinoma (9 papers, 2016 to 2026). A malignant neoplasm originating from the surface ovarian epithelium. "In ovarian cancer cells, MAP3K11 was found to enhance invasiveness by regulating expression of multiple mixed metalloproteinases." (PMID 26717044, 2016).
melanoma (7 papers, 2016 to 2025). A malignant, usually aggressive tumor composed of atypical, neoplastic melanocytes. "In melanoma cell lines, overexpression of miR-125b led to a decrease in MAP3K11 levels as well as decreased cell growth and invasiveness." (PMID 26717044, 2016). "Levels of MAP3K11 were found to be increased in several primary melanoma samples." (PMID 26717044, 2016).
colorectal cancer (5 papers, 2014 to 2020). A primary or metastatic malignant neoplasm that affects the colon or rectum. "Previous studies reported that MAP3K11 acts as an oncogene and participates in the tumorigenesis process in breast and colorectal cancer." (PMID 31527306, 2019). "MAP3K11 is an oncogene that promotes tumorigenesis in breast and colorectal cancer." (PMID 31527306, 2019).
gastric cancer (5 papers, 2008 to 2020). A primary or metastatic malignant neoplasm involving the stomach. "As was seen with miR-125b in murine pre-B cells, Song and colleagues have shown that miR-199a-5p was overexpressed in gastric cancer cells, associated with low levels of MAP3K11." (PMID 26717044, 2016). "However, in opposition to our findings, the authors correlated the increase in MAP3K11 levels with the observed decreased proliferation of gastric cancer cells." (PMID 26717044, 2016). "To directly demonstrate the functional role of PGC genes in cellular invasion, we performed siRNA experiments where five PGC genes (p53CSV, MAP3K11, MTCH2, CPSF6, SKIP) were silenced in poorly-metastatic AGS gastric cancer cells." (PMID 18636107, 2008).
lung carcinoma (5 papers, 2016 to 2025). "MAP3K11 was described as a target gene in lung cancer, contributing to the proliferation of activated epithelial cells." (PMID 41144480, 2025). "MiR-199a-5p can also inhibit the growth of lung cancer cells by targeting the MAP3K11 protein, as shown through in vivo and in vitro experiments of lung cancer." (PMID 35313857, 2022). "In lung cancer cells, MAP3K11 was found to be required for cell migration." (PMID 26717044, 2016).
prostate carcinoma (4 papers, 2012 to 2024). A carcinoma that arises from epithelial cells of the prostate gland. "Thus, to further explore the mechanism of MAP3K11 regulation of prostate cancer cell growth and AR transcription, we tested if MAP3K11 knockdown regulated AR Ser 650 phosphorylation since MAP3K11 is an upstream regulator of JNK activity." (PMID 22761715, 2012). "This study demonstrates the applicability of lentiviral-based shRNA for conducting phenotypic screens and identifies MAP3K11, DGKD, ICK, CIT, GALK2, and PSKH1 as regulators of prostate cancer cell growth." (PMID 22761715, 2012). "This study further demonstrates the applicability of lentiviral based shRNA for conducting phenotypic screens to identify targets involved in a variety of biological processes, and establishes MAP3K11, DGKD, ICK, CIT, GALK2, and PSKH1 as regulators of prostate cancer cell growth." (PMID 22761715, 2012).
pulmonary fibrosis (4 papers, 2017 to 2021). Chronic progressive interstitial lung disorder characterized by the replacement of the lung tissue by connective tissue, leading to progressive dyspnea, respiratory failure, or right heart failure. "As for the mechanism, miR-344a-5p inhibits the proliferation of myofibroblasts by targeting the mRNA of map3k11 to alleviate pulmonary fibrosis." (PMID 34381815, 2021). "Lnc-PCF can regulate map3k11 by targeting miR-344a-5p to promote the proliferation of activated epithelial cells, which results in pulmonary fibrosis." (PMID 29072702, 2017). "Mixed lineage kinase 3 (MLK3), a member of MAP3K family and also known as MAP3K11, is thought to be involved in several diseases, including cancer, pulmonary fibrosis, and ischemic brain injury." (PMID 32710001, 2020). "In addition, miR-344a-5p plays a vital role in anti-pulmonary fibrosis through MAPK signaling pathways, including map3k11." (PMID 34381815, 2021).
Cachexia (3 papers, 2020 to 2025). Severe weight loss, wasting of muscle, loss of appetite, and general debility related to a chronic disease. "Using genetically engineered xenograft mouse models, the activation of mitogen-activated protein kinase kinase kinase 11 (MAP3K11) by GDF-15 was identified as the key trigger for weight loss in animal models of cancer-related cachexia." (PMID 32508832, 2020).
gout (3 papers, 2023 to 2024). A condition characterized by painful swelling of the joints, which is caused by deposition of urate crystals. "The genes MAP3K11, KRTCAP2, and PCNX3 influence the function of macrophages, plasma cells, and MDCs, respectively, to increase gout risk." (PMID 38831441, 2024). "This study also identified 22 methylation sites related to gout, and genes that may increase the risk of gout, such as TRIM46, MAP3K11, KRTCAP2 and TM7SF2." (PMID 38831441, 2024). "Specifically, MAP3K11, as a serine/threonine kinase, may play a crucial role in the core inflammatory response of gout." (PMID 38831441, 2024). "The study also found that genes such as TRIM46, MAP3K11, KRTCAP2, and TM7SF2 could potentially elevate the risk of gout." (PMID 38831441, 2024). "Additionally, MAP3K11, a member of the mitogen-activated protein kinase family, could be involved in gout pathogenesis and is vital in activating c-Jun N-terminal kinase, a stress-activated protein kinase." (PMID 38202145, 2023). "Finally, we found by single-cell analysis that MAP3K11, KRTCAP2, PCNX3, and TM7SF2 demonstrate potential significant roles in the pathogenesis of gout." (PMID 38831441, 2024).
liver cancer (3 papers, 2019 to 2022). An epithelial or non-epithelial malignant neoplasm that arises from the liver. "A Chi-square test indicated that PTPN1 and MAP3K11 expression was also higher in HCC tissues than normal liver tissues in human liver cancer tissue microarray(TMA) slides purchased from U.S. Biomax (NO: LV1501) containing 10 normal liver and 120 HCC tissues." (PMID 31527306, 2019).
Parkinson disease (3 papers, 2015 to 2024). A progressive degenerative disorder of the central nervous system characterized by loss of dopamine producing neurons in the substantia nigra and the presence of Lewy bodies in the substantia nigra and locus coeruleus. "Notably, MAP3K11 demonstrated notable enrichment in acute myeloid leukemia within the high expression cohort, while associating with Parkinson's disease in the low expression group." (PMID 38965390, 2024). "Green module was obtained for five Parkinson’s disease FRGs (MAP3K11, SNX4, SIRT2, NUPR1, and ACSL4)." (PMID 38127902, 2023).
acne (2 papers, 2018 to 2024). An inflammatory process of the sebaceous glands which is characterized by comedones, nodules, papules and/or pustules on the skin. "However, we note a strong colocalisation between the acne association and an eQTL for MAP3K11, which encodes a stress-responsive protein kinase; this offers an alternative potential biological mechanism through which acne susceptibility is mediated by variation at this locus." (PMID 30542056, 2018).
colon cancer (2 papers, 2016 to 2022). "Silencing of MAP3K11 has been shown to decrease proliferation in colon cancer cells." (PMID 26717044, 2016).
coronary artery disease (2 papers, 2020 to 2023). "Similarly, QTLs for genes linked to coronary artery disease risk (e.g. LPL, SREBF1, GIT1, SKIV2L, MAP3K11/MLK3) were associated with colocalization sites linking coronary artery disease with mean platelet volume, lymphocyte, and/or reticulocyte counts." (PMID 32600345, 2020). "MAP3K11 has also been identified as a target for AS, as its inhibition can reduce the expression of key genes in coronary artery disease and the migration of vascular smooth muscle cells." (PMID 36969166, 2023).
esophageal cancer (2 papers, 2016 to 2023). A primary or metastatic malignant neoplasm involving the esophagus. "In our previous study, we found that miR-199a-5p bound and reduced the expression of MAP3K11 in esophageal cancer cells." (PMID 37835506, 2023). "The goal of this study was to examine expression of MAP3K11 in esophageal cancer cell lines and to characterize the interaction between MAP3K11 mRNA and miR-199a-5p in these cells using functional and binding assays." (PMID 26717044, 2016). "We also demonstrate that miR-199a-5p regulates MAP3K11 expression in these esophageal cancer cells through a direct interaction with MAP3K11 mRNA." (PMID 26717044, 2016). "In this study, we observed that MAP3K11 is markedly overexpressed in esophageal cancer cell lines." (PMID 26717044, 2016). "Similarly, our findings in esophageal cancer cells demonstrate that an increase in MAP3K11 levels, related to downregulation of miR-199a-5p, is associated with enhanced cellular proliferation." (PMID 26717044, 2016). "Although overexpression of miR-199a-5p and downregulation of MAP3K11 may affect proliferation through other mechanisms not evaluated in this study, these data support an important role for cyclin D1 in mediating the observed decreased proliferation in esophageal cancer cells." (PMID 26717044, 2016).
viral infection (2 papers, 2013 to 2022). "Gene ontology classes of the predicted cellular targets of HPV16-miR-H1-1 suggest important roles in host cell interactions of HPV 16, such as the cell cycle process (CUL3, CYP26B1, MAP3K11, PBRM1, SMC1A), especially the M phase (CYP26B1, PBRM1, SMC1A), which is important for viral infection." (PMID 23936163, 2013).
atherosclerosis (1 paper, 2022). A disease characterized by the build-up of fatty material and calcium deposition in the arterial wall resulting in partial or complete occlusion of the arterial lumen. "As a proof of concept, we evaluated a drug under development, which targets MAP3K11, on the expression of key genes involved in atherosclerosis and on the migration of VSMCs." (PMID 35246263, 2022).
Hepatitis C infection (1 paper, 2019). "The MAP3K11 protein possesses a SH3 domain that is critical in Hepatitis C infection to prevent MAP3K11 apoptosis." (PMID 32257606, 2019).
pterygium (1 paper, 2020). A wedge-shaped fibrovascular lesion arising from the bulbar conjunctiva and extending to the cornea. "Our present research presented that TGF-β and EGF activated the miR-199a-3p/5p-DUSP5/MAP3K11-MAPK axes in the EMT process of pterygium." (PMID 32867783, 2020). "Both expressions of miR-199a-3p and miR-199a-5p were significantly increased in pterygium (p < 0.0001), while expressions of DUSP5 (p = 0.0124) and MAP3K11 (p = 0.0005) were significantly decreased in pterygium." (PMID 32867783, 2020). "MiR-199a-3p-DUSP5 and miR-199a-5p-MAP3K11 axes regulated EMT in pterygium were characterized in our study." (PMID 32867783, 2020). "Downregulated protein expressions of DUSP5 and MAP3K11 in pterygium tissues were verified by western blot." (PMID 32867783, 2020). "Furthermore, it presented that miR-199a-3p and miR-199a-5p participated in the process of EMT induced by TGF-β and EGF, by targeting DUSP5 and MAP3K11 in pterygium." (PMID 32867783, 2020). "So, we speculated that miR-199a-3p and miR-199a-5p might target DUSP5 and MAP3K11 to function in EMT of pterygium." (PMID 32867783, 2020). "Accordingly, our study found that both DUSP5 and MAP3K11 implicated in MAPK signalling pathway, might be a potential therapeutic agent targeted specifically to reverse EMT in pterygium." (PMID 32867783, 2020). "The validated results in tissues showed that, compared with control conjunctival tissues, miR-199a-3p/5p were more overexpressed in pterygium, while DUSP5/MAP3K11 were lower expressed." (PMID 32867783, 2020). "TGF-β and EGF induce EMT of HCEs through miR-199a-3p/5p-DUSP5/MAP3K11 axes, which explains the pathogenesis of EMT in pterygium and may provide new targets for pterygium prevention and therapy." (PMID 32867783, 2020). "That is to say, TGF-β and EGF affected the expression of DUSP5 and MAP3K11 through regulations on expressions of miR-199a-3p and miR-199a-5p, so as to take part in the MAPK signalling pathway, further to promote the EMT of HCEs, and participate in the initiation and development of pterygium." (PMID 32867783, 2020).
cancer (34 papers, 2008 to 2025). A tumor composed of atypical neoplastic, often pleomorphic cells that invade other tissues. "We predicted that MAP3K11 levels should be high in the cancer cells lines if this interaction were biologically meaningful." (PMID 26717044, 2016). "Future efforts aimed at understanding the functions of MAP3K11 in cancer cells will require detailed evaluation of the activated signaling pathways." (PMID 26717044, 2016). "MAP3K11 acts as a tumor suppressor and a driver of cancer cachexia." (PMID 38217548, 2024). "And the PAPSS1, MAP3K11, and SPRED1 showed lower IHC scores in KIRC compared with para-cancer samples (p<0.05)." (PMID 38217548, 2024). "The immunohistochemistry indicated that the PAPSS1, MAP3K11, and SPRED1 showed lower IHC score in KIRC compared with para-cancer samples." (PMID 38217548, 2024). "Another five targetable gene dependencies had clinical inhibitors that have reached at least a phase II trial (BIRC2, ITGB1, MAP3K11, LDHA and PTPN1), with 3 having been applied to other cancer types (BIRC2, ITGB1, and LDHA)." (PMID 37997254, 2024). "The following IHC indicated that the PAPSS1, MAP3K11, and SPRED1 showed lower IHC score in KIRC compared with para-cancer samples." (PMID 38217548, 2024). "We functionally confirmed this association in siRNA knockdown experiments of five PGC genes (p53CSV, MAP3K11, MTCH2, CPSF6, and SKIP), which either directly enhanced the invasive capacities or inhibited the proliferation of AGS cancer cells." (PMID 18636107, 2008). "Furthermore, associations between MAP3K11, MTCH2 and CPSF6 to cancer have also not been previously reported." (PMID 18636107, 2008).
tumor (34 papers, 2013 to 2025). "Indeed, CEBPB and EP300, along with genes related to the Mitogen-Activated Protein Kinase (MAPK) signaling cascade such as MAP3K1, MAP2K2, and MAP3K11 were significantly upregulated in RMC tumor cells following treatment with nivolumab plus ipilimumab." (PMID 41290625, 2025). "For example, MAP3K11 fusion was detected in 23.5% (4/17) of adjacent non‐tumor tissues." (PMID 30903738, 2019). "In this investigation, it was observed that MAP3K1, MAP3K3, MAP3K5, MAP3K10, and MAP3K15 were upregulated in HCC tumor tissues, whereas MAP3K7, MAP3K8, MAP3K9, and MAP3K11 were downregulated in tumor tissues in GSE14520." (PMID 35311629, 2022). "For these tumor types, five cancer drivers were targeted only by NPs at < 100 nM, including Adenylate Cyclase 1 (ADCY1), Matrix Metallopeptidase 2 (MMP2), Aryl Hydrocarbon Receptor (AHR), Cyclin Dependent Kinase 2 (CDK2), and Mitogen-Activated Protein Kinase 11 (MAP3K11)." (PMID 31214023, 2019).
kidney disease (3 papers, 2021 to 2025). "To this end, we selected three MAP3K genes, Ask1 (Map3k5), Mlk2 (Map3k10), and Mlk3 (Map3k11), with connections to kidney disease for further analysis." (PMID 34962918, 2021). "Additionally, members of the MAP3K family, such as MAP3K5 (ASK1) and MAP3K14 (NIK), are known to be important in kidney disease, suggesting that modulating MAP3K11 activity could be a promising therapeutic strategy." (PMID 38892221, 2024).
MAP3K11 also shares sentences with these, for which no sentence is quoted: Myocardial fibrosis (11 papers); Cerebral ischemia (6); chronic heart failure (6); pancreatic cancer (6); cardiac hypertrophy (5); infection (5); hepatocellular carcinoma (4); triple-negative breast carcinoma (4); Alzheimer disease (3); glioblastoma (3); glioma (3); ischemia (3); acute myeloid leukemia (2); Breast tumors (2); depression (2); Encephalopathy (2); Hepatic fibrosis (2); Hepatic steatosis (2); metastatic disease (2); psoriasis (2); Sepsis (2); Anorexia (1); asthma (1); autoimmune disease (1); autoimmune encephalitis (1); bladder urothelial carcinoma (1); cardiomyopathy (1); cervical cancer (1); cognitive decline (1); Cognitive impairment (1).
A further 27 diseases each share a sentence with MAP3K11 in 1 paper.